GPR25 (G protein-coupled receptor 25)
Description:
Receptor for the C-X-C chemokine CXCL17, which plays a key role in lymphocyte homing. Ligand binding causes a conformation change that triggers signaling via guanine nucleotide-binding proteins (G proteins) and modulates the activity of downstream effectors, such as RhoA pathway. Activation by CXCL17 on lymphocytes activates the RhoA pathway, which regulates cytoskeletal dynamics and integrins, mediating lymphocyte recruitment into the respiratory, upper gastrointestinal, biliary and genito-urinary tracts.
Tractability: Small molecule: it belongs to a druggable protein family. Antibody: its Gene Ontology location is reachable by antibodies, with high confidence; UniProt places it where antibodies can reach, with medium confidence; UniProt predicts a signal peptide or a membrane-spanning region.
Target class: Family A G protein-coupled receptor; Membrane receptor
Gene: Protein-coding gene on chromosome 1 (200,872,981 to 200,874,178, forward strand). Ensembl gene ENSG00000170128.
Subcellular location: Cell membrane
Pathways (Reactome):
Signal Transduction: G alpha (s) signalling events
Gene Ontology:
Molecular function: C-X-C chemokine receptor activity; G protein-coupled receptor activity; protein binding
Biological process: chemokine-mediated signaling pathway; leukocyte chemotaxis; lymphocyte chemotaxis; lymphocyte migration into lymphoid organs; G protein-coupled receptor signaling pathway
Cellular component: plasma membrane; membrane
Genetic constraint (gnomAD): Loss-of-function variants: 2 observed, 1.13 expected, observed/expected ratio (o/e) 1.77, 90% interval 0.5 to 1.93. That is too few expected variants to judge how well the gene tolerates losing a copy. Missense variants: 501 observed, 412.46 expected, observed/expected ratio (o/e) 1.21, 90% interval 1.13 to 1.31. Synonymous variants: 280 observed, 211.48 expected, observed/expected ratio (o/e) 1.32, 90% interval 1.2 to 1.46.
Homologues: Orthologues: chimpanzee GPR25 (99% identical), macaque GPR25 (96% identical), pig GPR25 (78% identical), mouse Gpr25 (75% identical), rat Gpr25 (73% identical), dog GPR25 (67% identical), tropical clawed frog gpr25 (40% identical), zebrafish gpr25 (38% identical). Paralogues in human: GPR15 (31% identical), APLNR (29% identical), AGTR1 (28% identical), RXFP4 (26% identical), AGTR2 (25% identical), BDKRB1 (23% identical), BDKRB2 (22% identical).
Diseases named in the same sentence as GPR25 in open-access papers:
GPR25 is named in the same sentence as 5 diseases in open-access papers, as found by Europe PMC text mining. Sharing a sentence is not in itself a finding about the gene and the disease. The quoted sentences say what the papers report.
autoimmune disease (1 paper, 2020). A disorder resulting from loss of function or tissue destruction of an organ or multiple organs, arising from humoral or cellular immune responses of the individual to their own tissue constituents. "A recent report has suggested that an orphan G protein-coupled receptor 25 (GPR25), associated with blood pressure regulation and autoimmune disease, could be activated by both APLN and APELA in non-vertebrates, which is similar as APLN in decreasing the intracellular cAMP level." (PMID 33240613, 2020).
cancer (2 papers, 2019 to 2024). A tumor composed of atypical neoplastic, often pleomorphic cells that invade other tissues. "CELSR3, GPR25, EDNRB, and F2RL2 are significantly associated with patients’ survival in four cancers each, with an equal prevalence for lower and higher survival." (PMID 38723607, 2024). "The remaining four have no known cancer‐related function (KIAA1109, GPHN, GPR25, ZNF462)." (PMID 30809968, 2019).
GPR25 also shares sentences with these, for which no sentence is quoted: coronary artery disease (1 paper); infection (1); skin cutaneous melanoma (1).